PRMT5 (protein arginine methyltransferase 5)
Diseases named in the same sentence as PRMT5 in open-access papers (continued):
Sharing a sentence is not in itself a finding about the gene and the disease.
B-cell lymphoma (20 papers, 2015 to 2026). "Among the HSF1-binding proteins identified by MS, PRMT5, a methyltransferase, has been recognized as a key regulator in B-cell lymphomas." (PMID 40675964, 2025). "Depletion experiments confirm that PRMT5 protein expression is essential for B-cell lymphoma survival." (PMID 36167829, 2022). "We found that c-MYC and BCL-2 are key targets of the MSI2/PRMT5 axis, which drives resistance to PRMT5 inhibition in B-cell lymphomas." (PMID 36167829, 2022). "Next, we tested how the inhibition of MSI2 and PRMT5 affects c-MYC protein abundance in B-cell lymphoma cells." (PMID 36167829, 2022). "For example, GSK3368715, a PRMT1 inhibitor has been utilised in patients with B‐cell lymphoma, whilst several antagonists targeting PRMT5 have been investigated in many clinical trials for solid tumours and non‐Hodgkin lymphoma." (PMID 35090076, 2022). "In germinal centers, B-cell lymphoma 6 (BCL6) is methylated at residue R305 by PRMT5, giving rise to GC formation, affinity maturation, and B-cell lymphoma survival and proliferation." (PMID 36358861, 2022). "Both genetic and pharmacological approaches indicate that MSI2 and PRMT5 inhibition were synergistic in preventing growth of B-cell lymphoma cells." (PMID 36167829, 2022). "Anti-proliferative and anti-apoptotic effects are observed in PRMT5-depleted B-cell lymphoma using antisense oligonucleotides through the alteration of splicing of genes involved in lymphomagenesis." (PMID 36358861, 2022). "Aberrant expression of miR-92b and miR-96 is associated with enhanced protein arginine methyltransferase-5 (PRMT5) translation, which is overexpressed in aggressive B-cell non-Hodgkin’s lymphomas, including MCL and diffuse large B-cell lymphoma (DLBCL)." (PMID 34502399, 2021). "JNJ-64619178, a SAM-competitive inhibitor, binds to SAM- and the protein substrate binding domain of PRMT5 is being tested in a phase I clinical trial (NCT03573310) against B cell non-Hodgkin lymphoma and solid tumors." (PMID 32743345, 2020). "For example, in B cell lymphoma PRMT5 activity increases expression of cyclin D1 and c-myc in tumor cells by repressing miR-33b, miR-96 and miR-503." (PMID 32743345, 2020). "Protein arginine methyltransferase 5 (Prmt5), which catalyzes most symmetric dimethyl arginine protein modifications, is overexpressed in B cell lymphomas but its function in normal B cells is poorly defined." (PMID 30604754, 2019). "PRMT5 has garnered attention because it is overexpressed in GC-experienced and mantle cell human B cell lymphomas, correlating with poor prognosis." (PMID 30604754, 2019). "Interrogating the differential transcriptome at this early time point, while the CLL-like disease in Eμ-PRMT5/TCL1 mice is evolving through the pre-RT phase to morphologically resemble a large B-cell lymphoma, provides insight to mechanisms driving this progression." (PMID 36609611, 2023). "PRMT5 knockdown reduced proliferation in 6 cell lines across different subtypes of B-cell lymphoma." (PMID 36167829, 2022). "As the molecular events at the PRMT5 locus and how they deregulate associated expression during cellular transformation remain still elusive, our findings might represent a more common mechanism of PRMT5 deregulation in B cell lymphomas." (PMID 32555249, 2020). "Specifically, MYC has been shown to promote PRMT5 mRNA transcription in B cell lymphoma." (PMID 30941147, 2019). "This suggests that PRMT5 inhibition could be a novel therapeutic approach for B-cell lymphoma and PRMT5 inhibitors (PRMT5i) are currently in pre-clinical development." (PMID 29721185, 2018).
B-cell lymphoma (continued). "Taken together, PRMT5 and MSI2 cooperate in maintaining cell proliferation and the cell cycle program in B-cell lymphomas." (PMID 36167829, 2022). "The PRMT5 inhibitors, GSK3326595 and JNJ-64619178, are being evaluated in clinical trials in relapsed/refractory B-cell NHL including DLBCL (NCT02783300 and NCT03573310, respectively)." (PMID 34945817, 2021). "Furthermore, the SAM-competitive PRMT5 inhibitors CMP5 and HLCL61 were developed to suppress PRMT5 enzymatic activity in B-cell lymphoma and AML directly." (PMID 38474089, 2024). "To further study whether c-MYC plays a role in resistance to PRMT5 and MSI2 inhibition, we used the B-cell lymphoma cell line, P-4936 cells, that express c-MYC under the control of a tetracycline-inducible promoter." (PMID 36167829, 2022). "Concurrent PRMT5 and TCL1 expression resulted in a more rapid disease onset with increased lymph node involvement and overt lymphomagenesis that appeared to recapitulate disease behavior seen in human RT, representing a model to mimic large B-cell lymphomas that arise from CLL." (PMID 36609611, 2023).
liver cancer (19 papers, 2015 to 2025). An epithelial or non-epithelial malignant neoplasm that arises from the liver. "While HNF4α works to drive differentiation towards hepatic cellularity, PRMT5 antagonizes HNF4α expression assisting in liver cancer stem cell maintenance." (PMID 33768972, 2021). "The emergence of stem cells promotes drug resistance in liver cancer cells after PRMT5 suppressed the expression of HNF4α." (PMID 32859239, 2020). "Identifying its downstream targets will aid in elucidating the mechanism of PRMT5 in liver cancer development." (PMID 29441724, 2018). "The Tudor domain and α–helix present in SND1 are primarily accountable for reading the STD marks produced by PRMT5, and the further progression of molecular events could drive liver cancer." (PMID 40841409, 2025). "These insights are crucial for developing targeted therapeutic strategies aimed at disrupting the PRMT5-driven pathways implicated in HCC progression, ultimately improving patient outcomes and treatment efficacy in combating this aggressive form of liver cancer." (PMID 38666828, 2024). "Additionally, transcriptomic data demonstrated a significant increase in the PRMT5 expression level of HCC compared to dysplastic nodules with p < 0.01, indicating a progressive activation of PRMT5 during liver cancer development and progression." (PMID 38666828, 2024). "In addition, HNF4α has been shown to re-differentiate HCC cells into hepatocytes and inhibits EMT, thereby blocking the occurrence of liver cancer, however, PRMT5 antagonizes the expression of HNF4α and helps maintain liver cancer stem cells." (PMID 34513846, 2021). "In addition, there have been reports that PRMT5 and H4R3me2s bind to the promoter region of the hepatocyte nuclear factor 4α (HNF4α) gene in liver cancer cells." (PMID 32859239, 2020). "The essentiality of PRMT5 was further validated in another independent CRISPR screen in the NEJF6 cell line, another MYC-driven liver cancer cell line derived from ABC-Myc mouse liver tumor." (PMID 40326560, 2025). "LINC01138 promotes malignant behaviors by activating arginine methyltransferase 5 in liver cancer cells, revealing LINC01138/PRMT5 axis as an ideal target for liver cancer treatment." (PMID 36081999, 2022). "The focus of this review is on the overexpression of PRMT5 in HCC and there are numerous reports of elevated PRMT5 levels in liver cancer." (PMID 33768972, 2021). "Consistently, PRMT5 is a direct MYC target gene in the Eμ-myc lymphoma and liver cancer models." (PMID 35439169, 2022).
cervical carcinoma (18 papers, 2019 to 2025). A carcinoma arising from either the exocervical squamous epithelium or the endocervical glandular epithelium. "In patients with cervical cancer from the TCGA cohort, higher levels of PRMT5 expression were associated with worse outcomes in overall survival (OS), disease-specific survival (DSS), and progression-free interval (PFI)." (PMID 41463372, 2025). "High expression of PRMT5 in tumors is associated with poor prognosis in patients with cervical cancer, whereas PRMT5 deficiency leads to an increased number of tumor-infiltrating T cells and enhances their function." (PMID 40696413, 2025). "In order to further validate the antitumor potential of PRMT5 deficiency in cervical cancer treatment, we selected the PRMT5 inhibitor EPZ015666 to evaluate its possible therapeutic effects." (PMID 41463372, 2025). "As revealed by this study, the antitumor effect in cervical cancer cells is linked to the silencing of PRMT5, which promotes T cell recruitment and regulates CXCL10 expression." (PMID 41463372, 2025). "Overall, these findings indicate that high levels of PRMT5 expression in cervical cancer are associated with an unfavorable prognosis." (PMID 41463372, 2025). "Recently, Gao and colleagues have shown that PRMT5 associated with Snail and NuRD complex to induce methylation and repression of E-cadherin in cervical cancer." (PMID 35884488, 2022). "Overall, these data suggested that PRMT5 expression was increased in cervical cancer and that increased PRMT5 expression was associated with poor prognosis." (PMID 34522232, 2021). "Kaplan–Meier survival analysis showed that lower expression of PRMT5 was associated with improved survival of patients with cervical cancer." (PMID 33953349, 2021). "In addition, Cox proportional hazards regression analysis showed that PRMT5 high expression was a risk factor for incidence of cervical cancer." (PMID 34522232, 2021). "However, the underlying mechanisms by which PRMT5 contributes to the progression of cervical cancer and especially the tumor microenvironment remain poorly understood." (PMID 34522232, 2021). "In our previous study using a mouse cervical cancer model, silencing PRMT5 in tumor cells not only inhibited tumor growth but also elevated both the proportion and count of CD4+ and CD8+ T cells." (PMID 41463372, 2025). "In our study, we utilized EPZ015666 (also known as GSK3235025), a highly selective inhibitor of PRMT5, to treat cervical cancer transplanted tumor model, which showed significant antitumor activity." (PMID 41463372, 2025). "Further investigation is required to assess the effectiveness of PRMT5 inhibitors in patients diagnosed with cervical cancer." (PMID 41463372, 2025). "In our previous work, we identified PPM1B as an upstream regulator of the MP/PRMT5/histone signaling pathway, providing a novel mechanism of tumorigenesis in HeLa cells and cervical carcinoma." (PMID 41301499, 2025). "In summary, these findings elucidate a novel mechanism whereby PRMT5 depletion in cervical cancer cells triggers a CXCL10-mediated chemotactic response, enhancing CD8+ T cell infiltration and restricting tumor progression." (PMID 41463372, 2025). "This study revealed that knockdown of PRMT5 in cervical cancer cells resulted in elevated CXCL10 expression, which was associated with a higher accumulation of CD8+ T cells in the surrounding tumor microenvironment." (PMID 41463372, 2025). "Our findings elucidated a novel mechanism by which PRMT5 promotes immune evasion in cervical cancer and highlight the therapeutic potential of its inhibition." (PMID 41463372, 2025). "Cervical cancer patients with high PRMT5 expression can recruit more T cells, especially of CD8+ T cells." (PMID 41463372, 2025). "Subsequently, we investigate how PRMT5 affects the migratory and invasive capabilities of cervical cancer cells using scratch and transwell assays." (PMID 41463372, 2025).
cervical carcinoma (continued). "This study aimed to investigate the role of PRMT5 in shaping the tumor immune microenvironment of cervical cancer, with a specific focus on its regulation of CD8+ T cell infiltration." (PMID 41463372, 2025). "By controlling the transcription of the STAT1 gene through symmetric dimethylation of histone H3R2, PRMT5 knockdown in cervical cancer cells reduced PD-L1 expression and enhanced the quantity and activity of T lymphocytes inside the tumor microenvironment." (PMID 41154773, 2025). "PRMT5 expression was observed to be higher in cervical cancer tissues compared to normal tissues, suggesting its role in oncogenesis and its potential as a target for therapeutic target for cervical cancer intervention." (PMID 41463372, 2025). "Analysis of data from The Cancer Genome Atlas (TCGA) revealed elevated PRMT5 mRNA levels in cervical cancer tissues, which correlated with reduced immune cell infiltration and poorer patient prognosis." (PMID 41463372, 2025). "Nevertheless, this study provides a theoretical foundation for employing PRMT5 inhibitors as a therapeutic strategy against cervical cancer." (PMID 41463372, 2025). "Analysis of TCGA data revealed a correlation between elevated PRMT5 expression and unfavorable outcomes in patients with cervical cancer." (PMID 41463372, 2025). "One way to reduce the expression of PD-L1 and increase the quantity and activity of T lymphocytes in the tumor microenvironment is to knock down PRMT5 in cervical cancer cells." (PMID 41154773, 2025). "Nevertheless, these findings were based solely on in vitro experiments, and additional studies are necessary to elucidate how elevated levels of PRMT5 in tumor cells affect the onset and progression of cervical cancer in vivo." (PMID 41463372, 2025). "The observed impairment in migration and invasion suggested that PRMT5 played a key role in promoting the metastatic potential of cervical cancer cells." (PMID 41463372, 2025). "Then, the impact of PRMT5 gene on the migration, proliferation, invasion and apoptosis of cervical cancer cells was investigated, which highlighted its involvement in the initiation and progression of the disease." (PMID 41463372, 2025). "Stable PRMT5 knockdown cell lines were created using U14 cells and Siha cells to explore the role of PRMT5 in the biological characteristics of cervical cancer." (PMID 41463372, 2025). "Studies revealed that PRMT5, PRMT6, and PRMT8 mRNA and proteins are overexpressed in cervical cancer and are linked to poor survival in cancer patients." (PMID 36144454, 2022). "We have also demonstrated that NuRD(MTA1) complex physically associates with PRMT5 to promote the EMT process and strongly induced bone metastasis in cervical cancer." (PMID 35534547, 2022). "Snail1 also forms a repressive complex with NuRD and PRMT5 to contribute to histone deacetylation and methylation of E-cadherin in cervical cancer." (PMID 35884488, 2022). "Still, the fact that arginine methyl transferase inhibitor acts by reducing PRMT5 to inhibit cervical cancer growth suggests that specific mechanisms exist." (PMID 36144454, 2022). "PRMT splicing switches are emerging as essential role players in tumorigenesis, with PRMT5, 6, and 8 overexpressed in cervical cancer." (PMID 36144454, 2022). "Snail can also form a repressive complex with NuRD and PRMT5 and contribute to E-cadherin repression in cervical cancer." (PMID 35884488, 2022). "The protein levels of these markers correlated with mRNA levels, indicating that PRMT5 is positively correlated with the stemness maintenance of cervical cancer cells." (PMID 33953349, 2021). "The results indicated that PRMT5 promotes the tumorigenesis and metastasis of cervical cancer in vitro and in vivo." (PMID 33953349, 2021). "Trichostatin A suppresses cervical cancer cell proliferation and induces apoptosis and autophagy through regulation of the PRMT5/STC1/TRPV6/JNK axis." (PMID 34440894, 2021).
cervical carcinoma (continued). "The therapeutic effect of PRMT5 inhibitor was evaluated in a cervical cancer cell line transplanted tumor model." (PMID 34522232, 2021). "PRMT5 was positively correlated with the stemness maintenance of cervical cancer cells, suggesting that PRMT5 is a potential target of CSCs to overcome therapy resistance." (PMID 33953349, 2021). "We illuminated the mechanism of PRMT5 in the development of cervical cancer and explored the feasibility of treating cervical cancer with PRMT5 as a target." (PMID 34522232, 2021). "We demonstrated that PRMT5 promotes the invasion and tumorigenesis of cervical cancer and its expression is markedly upregulated in various human cancers." (PMID 33953349, 2021). "PRMT5 is known as an oncogene in various carcinomas, but at present the mechanism of PRMT5 has not been fully understood in cervical cancer, especially in the aspect of the crosstalk between tumor cells and T cells in the tumor microenvironment." (PMID 34522232, 2021). "Here, we found that in cervical cancer, PRMT5 expression was correlated well with the poor prognosis of disease." (PMID 34522232, 2021). "Overall, our study elucidated a new mechanism which PRMT5 knockdown in cervical cancer cells drives an antitumor function via reprogramming T cell-mediated response and regulating PD-L1 expression." (PMID 34522232, 2021). "Next, analysis of three published clinical datasets (GSE7803, GSE6791, and GSE67522) revealed that PRMT5 is highly expressed in cervical cancer cells than in adjacent normal tissues." (PMID 33953349, 2021). "To investigate the role of PRMT5 in cervical cancer progression, we collected 186 cervical cancer samples and adjacent normal tissues and performed tissue microarrays with IHC staining to examine PRMT5 expression." (PMID 33953349, 2021). "Next, we analyzed PRMT5 expression in cervical tissues from cervical cancer patients and controls using immunohistochemistry (IHC)." (PMID 34522232, 2021). "From tissue microarray, we found that PRMT5 expression in cervical cancer tissues was higher than that in normal cervix specimens." (PMID 34522232, 2021). "We demonstrated that PRMT5 promotes the invasion and tumorigenesis of cervical cancer in vitro and in vivo." (PMID 33953349, 2021). "PRMT5 was strikingly upregulated in cervical cancer and its expression was positively correlated with histological tumor grade." (PMID 33953349, 2021). "TSA suppresses cervical cancer cell proliferation and induces autophagic cell death through the regulation of the PRMT5/STC1/TRPV6/JNK axis." (PMID 34575981, 2021). "Further, we explored the molecular mechanism of PRMT5 promoting the expression of PD-L1 in cervical cancer cells, and studied the effect of PRMT5 on the number and function of T cells in the tumor microenvironment of a cervical cancer transplanted tumor model." (PMID 34522232, 2021). "The results in HeLa and Ca Ski showed that overexpression of PRMT5 resulted in an increased invasive potential of cervical cancer cells, whereas knockdown of PRMT5 showed the opposite result." (PMID 33953349, 2021). "Furthermore, the therapeutic efficacy of the selective PRMT5 inhibitor EPZ015666 was evaluated in a cervical cancer xenograft mouse model." (PMID 41463372, 2025). "Furthermore, the PRMT5 inhibitor demonstrated significant efficacy in cervical cancer using a mouse model." (PMID 41463372, 2025). "To summarize, our findings suggested that targeting PRMT5 could offer a promising therapeutic strategy for the treatment of cervical cancer." (PMID 41463372, 2025). "The results indicated that PRMT5 exerts an intrinsic effect on tumors, enhancing T cell infiltration into the tumor microenvironment while modifying the cytokine expression profiles specific to cervical cancer." (PMID 41463372, 2025). "Therefore, we validated the site of the antitumor effect of PRMT5 in cervical cancer treatment using a selective inhibitor (EPZ015666) targeting PRMT5." (PMID 41463372, 2025).